SATB1 (SATB homeobox 1)
Diseases named in the same sentence as SATB1 in open-access papers (continued):
Sharing a sentence is not in itself a finding about the gene and the disease.
cancer (continued). "SATB1 is a global genomic organizer that participates in activation and inactivation of genes and the differentiation of embryonic stem cells, thus is implicated in a variety of cancers and cancer progression." (PMID 31130823, 2019). "The SATB1-derived epitope identified may be used as a diagnostic marker as well as an immune target for development of cancer vaccines." (PMID 23437226, 2013). "Thus, as its aberrant expression promotes various types of cancers, the identification of a new SATB1 variant may be relevant for cancer-related studies." (PMID 25590302, 2015). "SATB1’s ability to regulate chromatin organization and gene expression underscores its role in cancer biology, particularly in metastasis." (PMID 40071088, 2025). "SATB1 is a key genome organizer that plays a crucial role in regulating gene expression by restructuring chromatin architecture, significantly influencing cancer progression." (PMID 40071088, 2025). "It is well established that β-catenin and SATB1 are upregulated in multiple Wnt-driven cancer types including CRC." (PMID 40689929, 2025). "Given its crucial involvement in cancer progression and metastasis, SATB1 has emerged as a promising target for novel therapeutic strategies." (PMID 40071088, 2025). "Research has shown that SATB1 promotes cancer progression primarily by inducing EMT by regulating EMT-related proteins." (PMID 40071088, 2025). "The antitumor effects of baicalein are mediated through various signaling pathways, including NF-κB, PI3K/Akt, mTOR, and TGF-β/Smad, making it a promising therapeutic agent for targeting SATB1 in cancer treatment." (PMID 40071088, 2025). "Mechanistically, SATB1 binds to specific regions of the myc promoter, inducing myc mRNA expression, in turn promoting cancer cell growth, increasing the number of S-phase cells, and enhancing invasiveness in vitro." (PMID 40071088, 2025). "This review delves into the molecular mechanisms of SATB1 in cancer and explores potential therapeutic approaches for targeting this key regulator in cancer treatment." (PMID 40071088, 2025). "SATB1 enhances the activity of ATP-binding cassette (ABC) transporter proteins—key players in reducing drug accumulation in cancer cells, thus promoting MDR—by altering their subcellular localization rather than expression." (PMID 40071088, 2025). "These investigations will be critical in determining the clinical applicability of SATB1 as a therapeutic target in cancer treatment." (PMID 40071088, 2025). "Several studies have showed that SATB1 affects Myc and Igh gene expression, thereby affecting chromatin stability and cancer cell progression." (PMID 40071088, 2025). "SATB1 overexpression can transform non-invasive cells into invasive, tumorigenic cells, while SATB1 knockdown in highly invasive cancer cells restores normal morphology and reduces their migratory and invasive capabilities." (PMID 40071088, 2025). "SATB1 siRNA-encapsulated immune liposomes binding to CD44 antibodies target cancer-initiating cells (CICs), reducing CIC proliferation by about 80% and reducing the CIC population by about 60%." (PMID 40071088, 2025). "Loss-of-function studies further validated the critical role of SATB1 in maintaining the invasive and proliferative characteristics of cancer cells." (PMID 40071088, 2025). "By combining gene silencing with chemotherapy and utilizing advanced delivery systems such as nanoparticles and immunoliposomes, SATB1-targeted therapies can offer a novel strategy to combat aggressive cancer types." (PMID 40071088, 2025). "In this review, we will explore the molecular mechanisms underlying SATB1’s contribution to cancer progression and metastasis, as well as the potential strategies for targeting SATB1 in cancer treatment." (PMID 40071088, 2025). "Further studies are needed to elucidate the mechanisms by which statins regulate SATB1 in other cancers." (PMID 40071088, 2025).
cancer (continued). "Further validation using the Pan-Cancer Human T Cell Atlas (scRNA-seq data) revealed high SATB1 expression in naïve and memory T cells, but marked reduction in exhausted subsets." (PMID 41372119, 2025). "We also detected this decrease in SATB1 expression with age in normal breast tissue of women with cancer in The Cancer Genome Atlas (TCGA) cohort (n=111, Wilcoxon adj." (PMID 39545637, 2024). "Strikingly, both CUX2 and SATB1 are overexpressed in certain cancer cells where their knockdown increases genomic DNA damage and impairs the capacity of cancer cells to proliferate." (PMID 36176767, 2022). "The special AT-rich sequence binding protein 1 (SATB1) contributes to cancer growth and metastasis, which makes its downregulation by siRNA a promising strategy for cancer treatment." (PMID 35456655, 2022). "In turn, the overexpression of SATB-1 in PC cells preserved surrounding CAFs, suggesting a circuit formed by CAF SDF1 and SATB-1 in cancer cells that promotes PC progression." (PMID 33671588, 2021). "While 39 (78%) carcinomas were SATB1 positive, only 11 (22.9%) benign tissue samples were strongly immunoreactive for SATB1 (p < 0.001)." (PMID 34961766, 2021). "Recently, SATB1 has been studied in multiple clinico-pathological settings, especially cancer-related – as reviewed by several groups." (PMID 33356851, 2020). "Although SATB1 expression was reduced at both the mRNA and protein levels across increasing grades of cancer, phosphorylation was increased, leading to functional changes." (PMID 33409278, 2020). "The independent prognostic role of CD8+SATB1+ TIL is suggestive of the potential utility of this biomarker in the context of cancer immunotherapy." (PMID 32612954, 2020). "Silencing SATB1′s expression with siRNA or shRNA was demonstrated to effectively supress cancer cell proliferation and invasion in vitro as well as in vivo in mice xenograft models." (PMID 31450715, 2019). "SATB1 was more internally positioned in five of the eight cancers where the gene was repositioned (62.5%) and more peripherally positioned in three cancers (37.5%)." (PMID 31681438, 2019). "The prognostic value of SATB1 differs depending on cancer type, which is probably a result of tissue-dependent regulatory functions of SATB1." (PMID 31737131, 2019). "SATB1 seemed to promote the mesenchymal phenotype of cancer cells by upregulating Vimentin and N-cadherin, as well as downregulating the key epidermal markers Claudin-1, β-catenin and E-cadherin;." (PMID 31450715, 2019). "Aberrant expression of SATB1 was reported in various types of cancers, including laryngeal squamous cell carcinoma, gastric cancer and breast cancer." (PMID 31130823, 2019). "Many recent studies have shown that SATB1 is highly expressed in several cancers and correlated with aggressiveness, poor survival, and clinicopathological properties." (PMID 31737131, 2019). "In this review, we briefly describe the prognostic significance of SATB1 expression in most common human cancers, and analyse its impact on EMT and metastasis." (PMID 31450715, 2019). "The impact of SATB1′s expression on cancer progression and metastasis seems to be especially significant in the case of gastrointestinal tumours." (PMID 31450715, 2019). "High SATB1 expression is usually correlated with high metastatic potential and poor prognosis of cancer." (PMID 31130823, 2019). "Special AT-rich sequence-binding protein 1 (SATB1) is a chromatin-remodeling protein that regulates gene expressions in different types of cancer." (PMID 31130823, 2019). "On the contrary, SATB1 mRNA expression was found to be significantly down-regulated in cancer cells in comparison to normal lung samples." (PMID 31450715, 2019). "SATB1 was in a statistically different nuclear position in 25% (2/8) of low Gleason score cancers, 33.3% (3/9) Gleason score 7 cancers and 50% (3/6) high Gleason score cancers." (PMID 31681438, 2019).
cancer (continued). "Its depletion had a reverse effect: an SATB1 knockdown in highly aggressive cancer cells was demonstrated to be enough to restore their normal morphology and decrease their migration and invasion abilities." (PMID 31450715, 2019). "Many studies analysing the impact of SATB1 on EMT-related proteins’ expression demonstrated its role as an inductor of the mesenchymal phenotype of cancer cells." (PMID 31450715, 2019). "The EMT process is not only related to actin but also related to its associated proteins such as SATB1, CFL1, or Rho kinases (ROCKI and ROCKII), whose overexpression was noted in many cancer types." (PMID 29581975, 2018). "Further research, however, is needed to explore the molecular mechanism of SATB-1 effect on cancer cell behavior." (PMID 30337520, 2018). "SATB1 overexpression outside the normal physiological context renders the cancer cells of a high metastatic potential." (PMID 28147311, 2017). "No similar key genes were found between TE-1 and MDA-MB-231 cells, also indicating SATB1 conducted its oncogenic role in different type cancers by regulation of different genes." (PMID 28147311, 2017). "In prostate and bladder cancer, overexpression of SATB1 can induce epithelial-mesenchymal transition (EMT) which leads to cancer cell invasion and metastasis." (PMID 28430598, 2017). "The novelty of this study is that it provided insight and evidence for further research to explore SATB1 as a target in cancer diagnosis and personalized treatment." (PMID 28430598, 2017). "The function of SATB1 in promoting cancer progression and metastasis was reported for the first time in breast cancer." (PMID 28636989, 2017). "In vitro study has shown that SATB1 can up-regulate genes that are known to promote cancer cell metastasis to the lung." (PMID 28430598, 2017). "Together with these previous findings, our results clearly indicate that SATB1 promotes cancer cell growth and invasion by altering the gene expression profile." (PMID 26701851, 2016). "SATB1 overexpression was observed in many types of human tumors, where it promotes cancer cell growth and metastasis by altering the gene expression profile." (PMID 26701851, 2016). "SATB1 expression in most cancers including CRC is associated with progression, poor prognosis and microsatellite instability (MSI), and SATB1 expression correlates with the loss of SATB2 expression." (PMID 26701851, 2016). "To explore the function of SATB1 in other aspects of cancer cells, we analyzed anchorage-independent growth (colony formation), cell migration and invasion." (PMID 26701851, 2016). "In order to further determine the effects of SATB1 expression on the cancer stem cell population, the effects of SATB1 overexpression in MCF-7 cells and SATB1 knockdown in BT-549 cells on CD44+/CD24− populations were investigated." (PMID 25586771, 2015). "We revealed nuclear and cytoplasmic immunoreactivity of the SATB1 protein in cancer cells as well as in cells of unchanged tissues; however, the nuclear expression was dominant." (PMID 25874491, 2015). "In the current study, SATB1 was identified to expand the cancer stem cell population, accompanied by the activation of the Notch signaling pathway, which promotes cancer stem cell self-renewal and the expression of the Snail1 and Twist1 genes that drive EMT." (PMID 25586771, 2015). "Cytoplasmic SATB1 expression was noted in cancer cells in 31/102 (30.4 %) CRC cases; however, unchanged large-intestine tissue enterocytes showed cytoplasmic immunoreactivity only in 3/39 (7.7 %) cases." (PMID 25874491, 2015). "Recent studies in cells with stable or transient knockdown or ectopic overexpression of SATB1 have further emphasized the functional relevance of SATB1 to carcinogenesis and multidrug resistance in cancer cells." (PMID 26422397, 2015). "Aberrant expression of MARBPs such as PARP, CUTL1, HMG (I/Y), RUNX1-3, SATB1, SATB2, PcG (polycomb group of proteins), SAFB1/2, SMAR1 etc. has been implicated in several cancers." (PMID 26325577, 2015).
cancer (continued). "Recent studies have shown that many types of cancer cells aberrantly express SATB1, which is positively correlated with poor prognosis and pathological properties." (PMID 26422397, 2015). "SATB1 nuclear expression was noted in cancer cells in 86/102 (84.3 %) of the analyzed CRC cases, whereas in enterocytes of unchanged large-intestine tissues, its expression was seen in 28/39 (71.8 %) cases." (PMID 25874491, 2015). "Nuclear and cytoplasmic SATB1 expression was noted in enterocytes as well as cancer cells of the analyzed tissues." (PMID 25874491, 2015). "A large number of target genes regulated by SATB1 involve in cancer cell proliferation, development and differentiation." (PMID 25956130, 2015). "SATB1 expression ratio (54.4%, n = 92) in cancer samples was significantly higher than that (17.5%, n = 7) in corresponding paracancerous normal samples (χ2 = 17.701, p = 0.000)." (PMID 25956130, 2015). "Special AT-rich sequence binding protein 1 (SATB1) is a global genome organizer initially identified in thymocytes and that recently attracted some attention as a putative cancer biomarker." (PMID 25326863, 2014). "Accordingly, we have knocked-down miR-21-5p expression in HCT116 cancer cells and observed an increased expression of SATB1." (PMID 25496125, 2014). "Special AT-rich binding protein (SATB1) is a global chromatin organizer that regulates gene expression and is involved in the modulation of malignant biological behaviors of cancer." (PMID 24675979, 2014). "There is increasing evidence that Special AT-rich sequence-binding protein 1 (SATB1) is aberrantly expressed in several cancers and is correlated with clinicopathologic parameters in these tumors." (PMID 23326301, 2013). "Special AT rich sequence binding protein 1 (SATB1) plays a crucial role in the biology of various types of human cancer." (PMID 24047082, 2013). "In 80 cases of cancer, SATB1 protein was positive in 47 (58.75%), which was significantly higher than in the matched normal colon mucosa (2.5%, P<0.01)." (PMID 23326301, 2013). "Our results are consistent with other reports showing that high expression of SATB1 promotes cancer progression in multiple human carcinomas." (PMID 24047082, 2013). "The frequency of SATB1 positive cells was also lower at the periphery of cancer tissue than those in the central zones of the cancer tissue." (PMID 23326301, 2013). "Since then, SATB1 has been established as a contributing factor to the development and progression of many different types of cancer, including breast, lung, prostate, colon and ovarian." (PMID 24260116, 2013). "SATB1 has been shown to be abnormally expressed in various types of cancer and is proposed as an oncogene which promotes malignancy." (PMID 23642278, 2013). "Relatively greater quantities of SATB1 mRNA were found in more poorly differentiated carcinomas, consistent with our immunohistochemistry findings." (PMID 23326301, 2013). "SATB1 mRNA was found in patient carcinoma samples and in all three of the cell lines we evaluated with RT-PCR." (PMID 23326301, 2013). "Further, once SATB1 expression reaches a threshold level, there is a positive correlation between the SATB1 level and metastatic potential of cancer cells." (PMID 23251624, 2012). "Although the role of SATB1 has been more extensively explored in the context of cancer, its impact on prognosis seems to be cancer –type-dependent." (PMID 22333599, 2012). "Kaplan Meier analysis and Cox proportional hazards modelling were used to explore the impact of SATB1 expression on cancer specific survival (CSS) and overall survival (OS)." (PMID 22935204, 2012). "We show here that ectopic expression of SATB1 alone is sufficient to convert MCF10A-1 cells to aggressive metastatic cancer cells both in culture and in vivo." (PMID 23251624, 2012).
cancer (continued). "Special AT-rich sequence-binding protein 1 (SATB1) is a global gene regulator that has been reported to confer malignant behavior and associate with poor prognosis in several cancer forms." (PMID 22935204, 2012). "In summary, Xist-mediated gene silencing capacity is preserved in cancer progenitors in which SATB1 has been identified as a silencing factor." (PMID 24212802, 2011). "Consequently, further studies are required to deepen our understanding of SATB1’s role in cancer biology, refine therapeutic approaches, and evaluate their potential side effects." (PMID 40071088, 2025). "Special AT-rich sequence-binding protein 1 (SATB1) expression and cancers." (PMID 40071088, 2025). "Conversely, SATB1 knockdown suppresses cancer cell proliferation and invasion." (PMID 40071088, 2025). "It appears that SATB1’s role can vary depending on the specific type of cancer." (PMID 39195213, 2024). "In addition to its oncogenic functions, SATB1 regulates cytokine expression and modulates the activity of T cells and DCs in development and cancer." (PMID 38416830, 2024). "Moreover, we suggest that deregulated production of the two SATB1 isoforms and their altered phase transitions resulting in protein aggregation, can contribute to the severity of pathologies such as cancer." (PMID 37635874, 2023). "Notably, in the context of cancer, the expression and functions of SATB1/2 and CUX1 have been extensively investigated in numerous studies." (PMID 37744879, 2023). "However, since then, other studies have uncovered that SATB1 is mainly expressed in the thymus, the bone marrow, the brain and in cancer cells." (PMID 35812421, 2022). "Strikingly, however, knockdown of CUX1 or SATB1 sensitized all tested cancer cell lines to ionizing radiation, whether they displayed high ROS levels or not." (PMID 36176767, 2022). "CAFs-derived SDF-1 promoting cancer cells SATB-1 expression." (PMID 34095111, 2021). "In addition, overexpression of SATB-1 in cancer cells was found to contribute to the process of gemcitabine resistance." (PMID 33808627, 2021). "Expression of SATB1 is altered in various types of cancers and may be involved in promoting metastasis." (PMID 33564000, 2021). "While the DNA repair function of CUT domain proteins (CUX1, CUX2, and SATB1) is required for the survival of cancer cells that exhibit high ROS levels, this biochemical activity does not appear to be essential to non-transformed cells in normal physiological situations." (PMID 34204734, 2021). "But an increased phosphorylation of SATB1 by PKC caused enhanced association with histone deacetylase (HDAC) 1, leading to altered transcription of genes, which contributed to the aggressive behavior of this cancer." (PMID 33409278, 2020). "Recently, a link between PD-1, SATB1 and cancer immunity has been reported suggesting that SATB1 may be a novel biomarker for prediction of the functional properties of T cells in the TME." (PMID 32612954, 2020). "Similarly, there was little statistical variation in RRDs among cancers in which the gene was more peripherally positioned, with the exception of SATB1." (PMID 31681438, 2019). "In peripheral tissues, the dysregulation of SATB1 expression is involved in various human cancers." (PMID 30803026, 2019). "There was a modest increase in the proportion of cancer specimens with either SATB1 or LMNA repositioned, compared to the PND, with increasing Gleason score, however, in the case of LMNA this may be due to the small sample size." (PMID 31681438, 2019). "The mechanism by which SATB1 regulate cancer development remains unclear and has been extensively studied." (PMID 31130823, 2019). "The important role of SATB1 in cancers has been fully elaborated." (PMID 29867574, 2018). "This indicates an important role of SATB1 in cancer progression through EMT promotion." (PMID 29581975, 2018).